CDH17 (cadherin 17)
Diseases named in the same sentence as CDH17 in open-access papers (continued):
Sharing a sentence is not in itself a finding about the gene and the disease.
tumor (continued). "Compared with control Nb-IR800, E8-IR800 produced much stronger fluorescent signals in tumor site at each time point (3 h, 6 h, 12 h and 24 h) post-injection, suggesting the superior specificity and binding activity of E8 nanobody in CDH17-overexpressing tumors." (PMID 36435809, 2022). "In addition, CAR-T targeting carcinoembryonic antigen (CEA), HER2, CLDN18.2, FOLR1, c-Met, CD133, and CDH17 had a significant anti-tumor effect in the corresponding target-positive GC mouse model and the tumor appeared partially or even complete regression." (PMID 36225938, 2022). "It is also likely that immune checkpoint inhibitor function contributes, at least in part, to the suboptimal anti-tumour immunity in CDH17 ‘high methylation’ tumours and that immune checkpoint blockade could be of interest to alleviate this." (PMID 36612154, 2022). "In the present study, we tested the combination effect of 5-FU and E8-PE38 on CDH17-postitive tumor control, and disclose that the combination treatment produces a better tumor repression than either drug alone, thus, indicating a novel therapeutic regimen for CDH17-positve GCs." (PMID 36435809, 2022). "This immunoassay could provide the selective quantification of both tumor markers (i.e., CDH-17 and IL-13sRα2) with respective LOD values of 0.03 ng mL−1 and 1.4 ng mL−1." (PMID 32079119, 2020). "Both CDH17 and IGF2BP1 were functionally associated with cell proliferation and tumor metastasis." (PMID 31427725, 2019). "Moreover, the tumor depthof invasion differed significantly between patients with positive CDH17 (CDH17+) andnegative CDH17 (CDH17-) GC." (PMID 26421870, 2015). "Results showed that after 35 days induction, Tet-induced group (tumor volume = 1849.08±423.46m3) exhibited a 2.27-fold higher growth progress rate versus Tet-free group (tumor volume = 814.04±234.69m3) (p<0.05), and induced CDH17 expression in tumor tissues can be analyzed by Western blotting." (PMID 24465527, 2014). "On the other side, overexpression of CDH17 facilitated MGC-803 GC tumor growth in nude mice." (PMID 24465527, 2014). "To further evaluate the effect of CDH17 knockdown on primary tumor growth, we then investigated whether in vivo delivery of CDH17 shRNA could impede the growth of an established tumor xenograft from parental AGS cells in nude mice." (PMID 23554857, 2013). "Additionally, the anti-tumor activity of CDH17-CAR-NK cells is synergistically enhanced by CD47–signal regulatory protein α (SIRPα) axis inhibitor CV1, likely through augmented macrophages activation and an increase in M1-phenotype macrophages in the tumor microenvironment." (PMID 40487639, 2025). "Moreover, the multivariable Cox proportional hazard model demonstrated that CDH17 immunohistochemical expression in tumor emboli may act as an independent prognostic factor." (PMID 40725206, 2025). "The VHH1-based second- and third-generation CAR-T cells were developed, and the third-generation CAR-T cells exhibited enhanced cytotoxicity towards NETs and gastrointestinal cancers in a CDH17-dependent manner in various tumor models without causing off-tumor toxicity." (PMID 40474230, 2025). "A possible explanation for keeping CDH17 levels in tumor emboli, even when tumor staging is T3, may be related to the early stages of their formation—detachment of tumor cells is possible through the loss of other adhesion molecules, while CDH17 remains stable." (PMID 40725206, 2025). "Considering that the E8-IR800CW NIR-II fluorescent probe exhibits outstanding tumor imaging capability and effectively directs imaging-guided precise tumor excision in CDH17-overexpressing CRC models, we next investigated whether CDH17-targeting Nb E8 fused with toxin PE38 could inhibit CRC." (PMID 38911825, 2024). "Furthermore, it cannot be ruled out that other alterations in the membrane localization of CDH17 may occur during the neoplastic process, due to the cellular plasticity and the different tissue architecture of the tumor." (PMID 38263178, 2024).
tumor (continued). "Cadherin 17 (CDH17), the member of cadherin superfamily with 7 extracellular cadherin domains and a short cytoplasm C terminus, has been documented to be overexpressed in tumor tissues of the digestive system, including stomach, colorectum, liver, and pancreas." (PMID 38911825, 2024). "To investigate this possibility, we stained slices of fixed and embedded tumor tissue from whole resected tumors with antibodies against three proteins we selected from among the most differentially expressed transcripts: Tenascin C (Tnc), Mucin 4 (Muc4), and Cadherin 17 (Cdh17)." (PMID 34936674, 2021). "In addition, Tet induced over-expression of CDH17 in TR-MGC803-CDH17_Over cells could promote the growth of tumor xenografts in vivo." (PMID 24465527, 2014). "Of note, cisplatin treatment did not result in any major changes in the cellular level and localization of CDH17, β-catenin, cyclin D1 and Rb in tumor xenografts, for which cisplatin might go for different antitumor mechanism not directly impacting the Wnt pathway." (PMID 24039755, 2013). "In SCLC, early investigational efforts are exploring CAR-T constructs directed against targets such as CDH17, GD2, and PTK7, which are selected based on tumor-enriched expression patterns similar to those leveraged by ADCs and T-cell engagers." (PMID 41562777, 2026). "Collectively, these results demonstrate that engineered OMV‐mediated photoimmunotherapy combined with CD47 nanobodies holds enormous potential to suppress primary and metastatic CDH17‐positive CRC and promote complete tumour eradication." (PMID 40240911, 2025). "The expression level of CDH17 on tumor tissues from this PDX model was initially determined by IHC, revealing high surface expression of CDH17 in PDX samples." (PMID 40487639, 2025). "Our findings demonstrate that CDH17-targeting CAR-NK cells effectively eliminate multiple GI cancers in both in vitro cell models and in vivo tumor models, including cell-derived xenograft (CDX) and patient-derived xenograft (PDX)." (PMID 40487639, 2025). "To explore the possible mechanism by which CV1 promotes the anti-tumor effect of CDH17-CAR-NK92 cells, we performed flow cytometry analysis for macrophages in the tumor microenvironment after treatment." (PMID 40487639, 2025). "Collectively, these results demonstrate that targeting CDH17-CAR-NK cells is successfully established and exhibits prominent in vitro anti-tumor performance." (PMID 40487639, 2025). "We also detected the expression of CDH17 and GUCY2C in 13 tumor cell lines by RT-PCR, and found that CDH17 and GUCY2C have a pronounced co-expression in various tumor cells." (PMID 40721409, 2025). "Tissue analysis revealed an absence of neuroendocrine cells and an abundance of T-cells in tumors treated with VHH1-28BBz-CDH17-CAR-T cells, indicating rapid tumor elimination." (PMID 41200177, 2025). "To augment the anti-tumor function of CAR-NK cells, we combine a high-affinity CD47 blocker, CV123, with CDH17-targeting CAR-NK cells." (PMID 40487639, 2025). "The most exciting clinical application of [89Zr]Zr-DFO-D2101 may be as a companion theranostic imaging agent for CDH17-targeted therapies, as the non-invasive nature of immunoPET offers distinct advantages over extant methods (i.e., biopsy) for the annotation of CDH17 expression by tumor tissue." (PMID 38625402, 2024). "Our results show that E8-Nb-IR800CW efficiently recognizes CDH17 in CRC cells and tumor tissues, produces high-quality NIR-II images for CRC tumors, and enables precise tumor removal guided by NIR-II imaging." (PMID 38911825, 2024).
tumor (continued). "Among these, Cadherin 17 (CDH17) stands out as one of the most significantly upregulated genes in GC, with documented roles in promoting tumor progression, invasion, and metastasis in affected patients." (PMID 38675228, 2024). "In the current study, we designed and fabricated an efficient bio-nanocomposite (CR@E8-EVs) with active tumor targeting capability through the integration of CR-DPA-T and CDH17 nanobody-engineered EVs." (PMID 37993888, 2023). "This occurs in addition to consequences on the tumour cell phenotype itself, notably induction of EMT, which interestingly is also a characteristic of the CDH17-high methylation CC cases in our study." (PMID 36612154, 2022). "RGD motifs in CDH17 and CDH5 promote tumor migration and invasion by activating α2β1 integrin signal and CDH6 activating αIIbβ3 integrin signal." (PMID 34930256, 2021). "Growing evidence indicates that CDH17 and IGF2BP1 are related to cell proliferation and tumor metastasis." (PMID 31427725, 2019). "Among the eight down-regulated genes, one is an oncogene (NEAT1), six are tumor-suppressor genes (ASS1, PTPRD, ISG15, TGFBI, SELENBP1, MEG3) and one gene serves as both an oncogene and tumor-suppressor gene (CDH17)." (PMID 30563222, 2018). "In multivariate analyses, tumor site(p = 0.02) histological differentiation (p = 0.02), TNM stage (p<0.001) and CDH17 expression (p<0.01) were independent prognostic factors for overall survival." (PMID 23554857, 2013). "Specifically, low levels of CDH17 immunohistochemical expression in the tumor core were significantly more correlated with the presence of EPNI, whereas high levels of CDH17 immunohistochemical expression were significantly more correlated with a low score of Bd (Bd1)." (PMID 40725206, 2025). "Furthermore, all articles focused on a single cancer/tumour type (CRC, GC, HCC), were published between 2009 and 2025, and reported CDH17 genetic modification or antibody inhibition in in vitro models." (PMID 41155133, 2025). "Notably, genes such as TFF3, CLDN3, CDH17, and REG4 exhibited specific expression in tumor cells, linking to the cancer progression." (PMID 40452847, 2025). "The framework for investigating the CDH17 profile in CRC and its relationship with clinicopathological characteristics was expanded by including patient survival as a major endpoint for assessing the prognostic influence of this biomarker on tumor behavior." (PMID 40725206, 2025). "Our results demonstrated that CDH17-CAR-NK92 cells were not detectable in the colon or stomach of tumor-bearing mice, despite the robust expression of CDH17 in these tissues." (PMID 40487639, 2025). "In contrast, CDH17 immunohistochemical expression in tumor emboli was not correlated with the remaining clinicopathological features (p > 0.05)." (PMID 40725206, 2025). "Concurrently with the search for novel targets like CDH17, significant attention is directed towards somatostatin receptors (SSTRs), well-established targets in NEN diagnosis and therapy due to their selective expression on tumor cells." (PMID 41200177, 2025). "Our research provides novel insights into CDH17 analysis in CRC through a complex assessment targeting the tumor core, invasive front, tumor emboli, and lymph node metastasis, as well as their relationship with a large panel of clinicopathological and survival characteristics." (PMID 40725206, 2025). "In this study, we utilized a CDH17-targeting Nb E8, identified by our group, conjugated with fluorescence molecule IR800CW with a NIR-II tail to examine its performance for CRC imaging and precise tumor removal." (PMID 38911825, 2024). "Additionally, a parallel staining of DSC1 and CDH17 in serial sections revealed a significant correlation between DSC1 and CDH17 expression at the tumor." (PMID 38263178, 2024).
tumor (continued). "After successfully conjugating E8 Nb with IR800CW and confirming the binding specificity and activity of E8-IR800CW to CDH17 in CRC cells, we subsequently assessed the in vivo performance of E8-IR800CW for CRC tumor imaging and imaging-guided precise tumor removal under NIR-II window." (PMID 38911825, 2024). "Together, these results demonstrate that CDH17 is up-regulated in CRC cells and tumor tissues and could be used as a membrane protein marker for the development of targeted imaging and therapy against CRC." (PMID 38911825, 2024). "We therefore performed IHC on the tumor and models, and observed no CDH17 expression, suggesting sensitivity to pevonedistat." (PMID 36816936, 2023). "CDH17 ‘high-methylation’ cases, showed increased expression of IL12B, IL10, CXCL9 and 10 and CCL2 compared to CDH17 ‘low-methylation’ cases, suggestive of a favourable cytokine/chemokine ‘milieu’ in these tumours." (PMID 36612154, 2022). "Another group has shown that tumor-derived exosomal miR-494 and miR-542-3p were able to modify distant lymph nodes and lung tissue toward a pre-metastatic phenotype suitable for tumor cell hosting, by targeting cdh17 and MAL, and cdh17 and TRAF4, respectively." (PMID 26258125, 2015). "Restoration of CDH17 expression in AGS and MKN-45 cells returned the cells to the parental phenotype, confirming that the anti-tumor effects of CDH17 knockdown were not due to off target effects." (PMID 23554857, 2013). "Finally, CD44, CD166, CD29, CEACAM5, cadherin 17, and biglycan were identified by mass spectrometry to be enriched in CD133+ tumour spheroid cells." (PMID 20332776, 2010). "Moreover, the univariable Cox proportional hazard analysis showed a significant correlation between CDH17 immunohistochemical expression and OS in N status (p = 0.007), LVI (p = 0.026), EMVI (p = 0.014), EPNI (p = 0.012), tumor emboli (p = 0.042), and prognostic stage group (p = 0.007)." (PMID 40725206, 2025). "However, the endocytic activity of the CDH17 monoclonal antibody is much lower than that of the GUCY2C monoclonal antibody, which may reduce the anti-tumor activity of the CDH17 monoclonal antibody ADC." (PMID 40721409, 2025). "Notably, although we tested the biohybrid‐engineered bacteria in three tumor models with high CDH17 expression, and examined their anti‐tumor performance and mechanisms, we only conducted TME reprogramming experiments in a syngeneic colorectal murine tumor model in immunocompetent mice." (PMID 38888519, 2024). "The BsADC targeting CDH17 and GUCY2C can increase the binding and endocytosis activities, thereby enhancing the anti-tumor activities without worrying too much about toxicity issues." (PMID 40057807, 2025). "We established that the CDH17-YAP pathway is active in CTC-TJH-01 clusters and that its suppression can reduce their chemoresistance, although it does not halt tumor growth." (PMID 39994505, 2025). "Surprisingly, CDH17-CAR-NK92 cells significantly inhibited ASPC1 tumor burden in mice compared to C9-CAR-NK92 cells, which did not exhibit any tumor inhibition." (PMID 40487639, 2025). "Cadherin-17, depicted in the tumor metastasis network, was identified by TCSG exclusively in the tumor parenchyma, with no detection in 2D-grown A549 cells or normal lung tissue." (PMID 29899869, 2018). "Thus, the intestinal cell-cell adhesion protein, cadherin 17 (CDH17), is expressed in HCC as an SV lacking exon 7 (ΔEX7CDH17), which correlates with decreased OS and higher tumor recurrence." (PMID 35008179, 2021).
cancer (56 papers, 2013 to 2026). A tumor composed of atypical neoplastic, often pleomorphic cells that invade other tissues. "Our results aligned with previous studies, revealing high CDH17 expression in these three cancer types, with expression levels positively associated with malignancy." (PMID 38888519, 2024). "CDH17 is a cadherin protein that plays a role in the gastrointestinal tract and pancreatic ducts and has been linked to cancer metastasis." (PMID 38608841, 2024). "The results demonstrated that overexpression of CDH17, as measured by the M Score, was associated with advanced cancer staging and was identified as an independent prognostic factor for OS and RFS." (PMID 39617741, 2024). "Inrecent years, several intrinsic genetic factors such as expression of the cadherin-17gene (CDH17) have been implicated in the carcinogenesis and progressionof human cancers, and have become a popular research topic." (PMID 26421870, 2015). "Numerous studies have reported elevated levels of CDH17 in various human cancers, linking expression of this protein to prognosis and risk assesment." (PMID 23554857, 2013). "The biological function ofCDH17 remains unknown, although many studies have demonstrated elevated CDH17 levels invarious human cancers, and linked it to prognosis and risk evaluation." (PMID 26421870, 2015). "To further explore the role of the CDH17-YAP pathway in the cancer stemness and drug resistance of suspended CTCs, we utilized siRNA to downregulate CDH17 protein expression in CTC-TJH-01 cells." (PMID 39994505, 2025). "Across all five included studies, inhibition of CDH17 consistently suppressed Wnt/β-catenin signalling and its cancer-promoting effects." (PMID 41155133, 2025). "Our objective is to understand the role of CDH17 in cancer progression and to characterise interactions between CDH17 and the canonical Wnt pathway in human cancers." (PMID 41155133, 2025). "In cancer cells, the interaction of CDH17 with the integrin α2β1 promotes the activation of several pathways, ultimately leading to increased cell adhesion and proliferation." (PMID 40595509, 2025). "Collectively, we demonstrate that CDH17‐targeting nanobody‐engineered OMVs can directly initiate the activation of the STING pathway in cancer cells, which in turn induces ICD occurrence." (PMID 40240911, 2025). "Collectively, these results demonstrate that nanobody‐engineered OMVs are successfully prepared with the expected nanovesicle structures, and that designed Nb289‐OMVs can specifically recognise CDH17 expressed in human and murine cancer cells." (PMID 40240911, 2025). "Together, these findings provide strong evidence that CDH17 functions as an upstream activator of the Wnt/β-catenin pathway, with its suppression pathway activity consistently affected across diverse cancer models." (PMID 41155133, 2025). "Mice transplanted with SW1463 and LS1034 cancer cell lines were injected intravenously with CDH17-ADC, GUCY2C-ADC, or CDH17 x GUCY2C BsADCs." (PMID 40721409, 2025). "Our results underscore the critical role of tissue-specific cadherins, such as CDH17, in regulating pluripotency and stem cell characteristics, highlighting their broader significance in cancer biology." (PMID 40595509, 2025). "Taken together, these results demonstrate that the nanobody Nb289 can be employed for imaging detection of CDH17‐positive cancers and has the potential for delivering various payloads for therapy against CDH17‐expressing tumors." (PMID 38888519, 2024). "Due to the superior binding activity of Nb289 and Nb535 among all the nanobodies to human and murine CDH17 proteins, they were further investigated for in vitro cancer cell studies." (PMID 38888519, 2024). "Flow cytometry and immunofluorescent staining of several gastric (IM95, MKN45, TMK1, and AGS), colorectal (HCT116 and Colon26), and pancreatic (ASPC1 and PancO2) cancer cell lines confirmed that CDH17 was predominantly expressed on the cell membrane surface." (PMID 38888519, 2024).